TNF (tumor necrosis factor)
Diseases named in the same sentence as TNF in open-access papers (continued):
Sharing a sentence is not in itself a finding about the gene and the disease.
cancer (continued). "In TNF-α-resistant cancer cells, the combined pro-apoptotic signals are overwhelmed by pro-survival machinery, leading to cancer progression." (PMID 38698424, 2024). "Cancer cells produce a range of pro-inflammatory cytokines, including tumor necrosis factor-alpha (TNF-α), interleukin-6 (IL-6), and interleukin-1 (IL-1)." (PMID 39451734, 2024). "Secretome from TNF-α treated cancer cells induced an immunomodulatory and chemotactic phenotype in MSC and cancer-associated fibroblasts (CAFs)." (PMID 39310770, 2024). "Measurement of the levels of inflammatory cytokines (HMGB1, tumor necrosis factor-alpha [TNFα]) and lipid peroxides (4HNE) in the cancer ascites showed increased levels for all cytokines compared with the control mouse peritoneal lavage." (PMID 39000167, 2024). "The results also showed that cytokine and receptor activity were enriched in AML, further validating the role of inflammatory signals such as IL-6 or TNF-α in the development of cancer stem cells." (PMID 39877157, 2024). "A wide range of substances and therapeutic methods has been developed to enhance immunotherapy effects in cancer patients, although combined application of sphingolipid-targeting agents and TNF-α pathway activating methods seems neglected." (PMID 38698424, 2024). "TNF later turned out to be one of the crucial discoveries of Old, as a key cytokine involved in cytolysis of cancer cells." (PMID 39767654, 2024). "Meanwhile, KEGG enrichment analysis indicated that apoptosis, TNF signaling pathway in cancer were enriched." (PMID 39376555, 2024). "First, it was the only cytokine higher in that disease; furthermore, all who developed cancer in 5-year follow-up had the highest levels of TNFα at baseline." (PMID 38051374, 2024). "Lymphocytes also release cytokines such as TNF and interferon-gamma to impede cancer cell development." (PMID 38935663, 2024). "Interleukin 6 (pro-inflammatory) can activate the JAK/STAT signalling pathways, preventing apoptosis and, along with TNF-α, facilitating angiogenesis and cancer growth." (PMID 38191592, 2024). "On the other hand, high TNF-α expression has been described as a predictor of poor survival in cancer patients." (PMID 39408920, 2024). "The TNF-α-EV-SPIONs nanoparticles exhibit enhanced targeting capabilities and reduced toxicity, offering promising anti-cancer effects." (PMID 38164177, 2024). "The phospholipase A2 activity of PRDX6 promotes tumor necrosis factor alpha‐induced cancer cell death in HCC." (PMID 37994394, 2024). "A recently described phenotype of cancer-associated adipocytes (CAAs) (characterized by the production of CCL5, CCL2, IL-6, and TNF-α) has been shown to promote the proliferation and invasion of tumor cells, as well as neovascularization." (PMID 38667297, 2024). "The use of CIS in cancer therapy is usually accompanied by inflammation and increased pro-inflammatory cytokines like tumor necrosis factor-alpha (TNF-α), inducible nitric oxide synthase (iNOS), interleukin-1 beta (IL-1β), and Interleukin-6 (IL-6)." (PMID 39765772, 2024). "The upregulation of PD-L1, TGF-β, IL-6, and TNF-α observed in c-Mel represents further evidence on the immunosuppressive roles of TAFs and TAMs on cancer cells." (PMID 37612575, 2024). "Anti-TNF-α MABs, such as infliximab, adalimumab, and anti-golimumab antibody, that have been evaluated for their disease stabilization effect in cancer, also act by hindering NF-κB activation." (PMID 39767654, 2024). "NF-κB mainly serves as an anti-apoptotic signal and JNK mediates the pro-apoptotic effect of TNF on cancer cells." (PMID 39206193, 2024). "Tumor necrosis factor-alpha in the body is linked to increased expression of the chemokine receptor CXCR4 and its ligand CXCL12 in cancer cells, both in lab-cultured cells and patient-derived samples." (PMID 39830670, 2024).
cancer (continued). "PD-1 blockade promotes a Th1/Th17 response via enhanced production of interferon γ, interleukin (IL)-2, tumor necrosis factor-α, IL-6, and IL-17 and reduction of Th2 cytokine profiles in patients with cancer." (PMID 39823053, 2024). "It would be a promising approach to treat cancers by targeted delivery of TNFα through an inactive adoptive cell in combination with an IAP antagonist." (PMID 39105847, 2024). "Previous studies have also shown the upregulation of glycolysis by TNFα in many cancer cell types, endothelial cells, and immune cells." (PMID 39184151, 2024). "In contrast, SM164 plus TNFα markedly increased trabecular bone volume in the bones with cancer, suggesting that their combined therapy protected these bones from cancer-induced osteolysis." (PMID 39105847, 2024). "Increased TNF-α and TNF-R expression has been implicated in various cancers, including NSCLC, indicating a significant role for these molecules in the disease’s development and progression." (PMID 38339276, 2024). "This review focuses on ICKs designed with the most impactful cytokines in the cancer field: IL-2, TNFα, IL-10, IL-12, IL-15, IL-21, IFNγ, GM-CSF, and IFNα." (PMID 39204319, 2024). "The similarity of this pattern of behavior to that induced by osteocyte conditioned media, implicates TNF‐α as a potential cytokine secreted by osteocytes to regulate cancer cell proliferation and migration." (PMID 37967351, 2024). "The analysis revealed that gene sets indicative of invasiveness of cancer, including TNFα signaling via NF-kB, EMT, and hypoxia, are upregulated in ELAVL2-low GBM patients." (PMID 38548861, 2024). "Silencing cytokine-inducible SH2 (CIS) containing protein in NK cells increases production levels of IFN-γ and TNF-α, enhancing cancer cells apoptosis mediated by allogeneic NK cells and improving overall survival in mice with GBM." (PMID 38720342, 2024). "In the context of oral cancer, specifically squamous cell carcinoma of the head and neck, recent research has demonstrated that the release of noradrenaline by sympathetic neurons stimulates the production of TNF-α by cancer cells." (PMID 38433844, 2024). "Incubation of these cancer cell lines with tumor necrosis factor-α (TNF-α), which activates NF-κB, also induced PD-L2 expression to a larger extent than PD-L1." (PMID 38267628, 2024). "Curcumin can inhibit the activity of CSN5 in various types of cancer and suppress TNF-α-induced PD-L1 stability in cancer cells." (PMID 39748950, 2024). "TNFα promoted PANX1 cleavage via a caspase 8/3-dependent pathway to enhance cancer cell immunogenicity, leading to dendritic cell maturation and T-cell activation." (PMID 38195677, 2024). "In TNF-α stimulated cell lines, 1000μg/ml ethanolic extract significantly reduced the regulation of the NF-kB pathway, which plays a role in cancer progression (p<0.001)." (PMID 39687882, 2024). "Although TNF was initially named for its tumoricidal activity, later studies aimed at exploiting TNF to treat cancer revealed that the TNF-TNFR1 axis can also promote cell survival and proliferation via activation of NFκB." (PMID 39615678, 2024). "Studies have shown an increase in various inflammatory markers in the peripheral circulation during cancer, including IL-1, IL-6, IL-1β, and TNF-α in different types of cancer." (PMID 38473351, 2024). "NF-κB is one of the most well-known molecular pathways involved in cancer and has been considered a prototypical pro-inflammatory signaling pathway, activated by cytokines such as interleukin 6 (IL-6) and TNF-α." (PMID 39596471, 2024). "Most of the downregulated genes were, in turn, involved in the transcriptional mis-regulation in cancer and the downregulation in TNF-α signalling." (PMID 39205185, 2024).
cancer (continued). "Studies have shown that TNF-α can trigger the movement of RelA into the nucleus, which in turn promotes the spread of cancer cells and aids their transition into a more aggressive form." (PMID 39834817, 2024). "M1 macrophages, known for their antitumor properties, can produce proinflammatory cytokines such as IL-12 and TNF-α, as well as oxygen intermediates, all of which are crucial in countering cancer." (PMID 39354474, 2024). "It was also reported that TNFα secreted by macrophages can inhibit VDR expression in cancer cells, whereas upregulation of VDR decreases the metastatic potential of 4T1 cells." (PMID 38355711, 2024). "Several studies in the field of autoimmune diseases and cancer have found promising results from the use of bs-Abs targeting TNF-α and other receptors." (PMID 39609700, 2024). "TNF-α is the main cytokine involved in inflammatory reactions and the first cytokine used in cancer treatment that promotes antitumor activity through inflammatory and immune responses and induces cancer cell death." (PMID 39120359, 2024). "In conclusion, dual COX-2/TNF-α suppression represents an innovative approach for developing new drugs for pain relief and cancer therapy, which should be pursued with strong emphasis." (PMID 39830670, 2024). "Soluble cell factors, including IL-6, TNF, IL-4, IL-1 family cytokines, and IL-13, not only facilitate the metastasis and invasion of cancer cells but also control MDSCs accumulating and activating in the TME." (PMID 38720342, 2024). "Genomic Set Enrichment Analysis (GSEA) revealed enrichment of the TNFα signaling pathway via the NFκB and mTORC1 signaling gene clusters within cancer cells expressing ONECUT2." (PMID 38997271, 2024). "Current scientific evidence indicates that miRNAs play an important role in cancer, being involved in the regulation of different cancer mechanisms such as apoptosis, TNFα signaling, hypoxia, or inflammatory response." (PMID 39125744, 2024). "This study reviews mechanisms of TNF-α-resistance in cancer cells, with emphasis on the pro-survival and immunomodulatory effects of sphingolipids." (PMID 38698424, 2024). "In tandem, CD4+ T cells further potentiate the sensitivity of cancer cells to ferroptosis by secreting TNF-α, which binds to TNF-α receptor 1 (TNFR1) on the cancer cells." (PMID 38217037, 2024). "We postulate that increased α2-6 sialylation of TNFR1 and Fas protects cancer cells from apoptosis induced by TNF and FasL, both of which are highly enriched within an inflammatory milieu." (PMID 39615678, 2024). "Due to these combined actions, dual COX-2/TNF-α inhibitors have been investigated as chemopreventive agents and as adjuvants in cancer therapy." (PMID 39830670, 2024). "The authors further showed that crocin inhibited cancers by downregulating the transcription of cytokines such as tumor necrosis factor-α [TNF-α], nuclear factor-κB [NF-κB], interleukin-6 [IL-6], interferon-γ, COX-2, IL-1β, and inducible NO synthase [iNOS]." (PMID 38891276, 2024). "TNF, a proinflammatory cytokine secreted mainly by myeloid cells and also by cancer cells, plays a pivotal role in cancer progression and inflammation." (PMID 38561856, 2024). "For example, adipocyte-released leptin promotes epithelial–mesenchymal transition (EMT) in breast cancer cells by activating the PI3K/AKT signaling pathway, and TNF-α and IL-6 secretion upregulates PD-L1 in cancer cells to promote immune evasion." (PMID 38714880, 2024). "The findings on cancer cell growth inhibition by ethanolic AML extract were supported by a dose-dependent downregulation in the expression of the pro-inflammatory cytokine TNF-α." (PMID 39687882, 2024). "The authors postulated a potential correlation between different cancer subtypes and the inflammatory adipose microenvironment rich in IL-6 and TNF-alpha, along with heightened levels of IGF-1 observed in obese patients." (PMID 38611106, 2024).
cancer (continued). "The observed changes in UPE exhibited an additional trait, since they occurred as an oscillatory pattern, with the TNF-α-induced oscillations emerging as a significantly different damped signature based on the type of the cancer cell line being investigated." (PMID 39357824, 2024). "The main mechanism is that after treatment with SeNPs, elevated ROS accumulation in cancer cells activates TNF and interferon regulatory factor 1 (IRF1), which ultimately leads to an increase in RIP1 protein expression inducing necroptosis." (PMID 38652105, 2024). "At the molecular level, induction of CTL-mediated ASI is one of the primary mechanisms of anti-tumor immunity, which is carried out by releasing cytokines such as IFN-γ/TNF-α, perforin, and granzyme that eradicate cancer cells." (PMID 39767654, 2024). "The soluble antigens such as TNF-α and VEGF can have deleterious biological effects associated with various diseases such as inflammatory diseases and cancer." (PMID 38533506, 2024). "Tumor necrosis factor (TNF)-related apoptosis-inducing ligand (TRAIL) is well known anti-cancer therapeutic agent." (PMID 39030546, 2024). "In the group with a history of previous cancer, five patients received anti-TNFα treatment, seven received anti-IL-23 biologics, three were treated with anti-IL-17 agents, and one patient received ustekinumab." (PMID 38610706, 2024). "Gut microbes regulate inflammatory factors such as tumor necrosis factor-α (TNF-α), interleukin-1 (IL-1), and NF-κB to activate or suppress cancer-related inflammation." (PMID 38794174, 2024). "ICAM-1/CD54 is constitutively expressed at relatively low levels on the endothelium, leukocytes, and many other cell types (including cancer cells), but its expression is dramatically increased by multiple inflammatory stimuli, including TNFα, IFN-γ, and IL-1." (PMID 38542421, 2024). "Canonical NF-kappa B signalling inhibition has been proposed for cancer therapy and further research should analyse TNF-alpha and CD40 roles as SLNs predictive markers." (PMID 39199652, 2024). "The pro-inflammatory cytokine TNF-α plays a pivotal role in cancer metastasis by inducing the expression of CAMs on HUVECs." (PMID 38738179, 2024). "TNFα-dependent and radiation-induced cytotoxicity is attenuated by NF-κB activity in many cancers, including HNSCC." (PMID 39392349, 2024). "Various inflammatory factors that affect the occurrence and progression of cancer, including IL-6, IL-1, and TNF-a dysregulation, can all affect cholesterol synthesis." (PMID 38605235, 2024). "Meanwhile, RT has been shown to prevent cancer-induced myofiber atrophy, reduce inflammation by reducing the expression of TNF-α and IL-6, and mitigate oxidative damage by inducing cytochrome oxidase." (PMID 38791998, 2024). "Using a series of co‐culture, conditioned media, human cancer spheroid, and organ‐on‐a‐chip experiments, this study reveals that osteocytes suppress cancer cell proliferation and increase migration via tumor necrosis factor alpha (TNF‐α) secretion." (PMID 37967351, 2024). "Some studies have shown that the herbs extraction emodin can treat cancer by activating TNF‐a induced necroptosis." (PMID 38800967, 2024). "The principal signaling pathways implicated are the cancer pathway, MAPK, AGE–RAGE, EGFR, TNF, PD-L1, and HIF-1 pathways." (PMID 39612458, 2024). "Interferon-γ and IL-6 also have a similar effect to TNF-α on lipid metabolism in animal studies of cancer cachexia." (PMID 39114348, 2024). "KEGG pathway analysis inferred that the main signaling pathways of Avn intervention in AS were cancer, lipid and AS, leukocyte transendothelial migration, and TNF signaling." (PMID 39705422, 2024).
cancer (continued). "Increases the production of TNF-α-specific IgG and IgM in the body, promoting an immune response against cancer cells." (PMID 38543481, 2024). "DEGs were implicated in leukocyte transendothelial migration, PI3K-Akt, chemokine, NOD-like receptors, TNF signaling pathways, and pathways in cancer." (PMID 39273699, 2024). "Numerous studies have reported that elevated systemic inflammation signified by increased levels of IL‐6, TNF‐α, and CRP contributes to cancer cachexia and is associated with poor survival." (PMID 38725139, 2024). "CD8+ T cells can specifically detect and eliminate cancer cells by secreting effector cytokines (tumor necrosis factor (TNF) and interferon-γ (IFNγ)) or cytotoxic molecules (such as perforin and granzymes)." (PMID 39074262, 2024). "A number of clinical studies have analyzed the therapeutic value of TNF-TNFR antagonists in cancer treatment." (PMID 39206193, 2024). "Mustard seed extract was also reported to act by suppressing the expression of lymphocyte activating factor, tumor necrosis factor alpha (TNF), and interleukin (IL)-6 mRNA, and inhibiting Langerhans cell migration in the epidermis of Albion mice cancer models." (PMID 39201724, 2024). "TNF-α is a mediator of the immune response in various immunological diseases, infections, and types of cancer." (PMID 39408920, 2024). "Smac mimetic compounds (SMCs) are small molecule drugs that sensitize cancer cells to TNF-α-induced cell death and have multiple immunostimulatory effects through alterations in NF-κB signaling." (PMID 39147758, 2024). "Resistance to TNF-α/TRAIL is cancer-specific and can be mediated by several anti-apoptotic mechanisms." (PMID 38698424, 2024). "Approaches that target the extrinsic apoptotic pathway to induce cancer death include the use of DR agonists such as Fas ligand, tumor necrosis factor-alpha (TNFα), TNF-related apoptosis-inducing ligand (TRAIL), Apo2L/TRAIL, and CD95L/FasL 26,36." (PMID 38169587, 2024). "In cancer cachexia, inflammatory cytokines such as interleukin (IL)-1, tumor necrosis factor (TNF)-α, IL-6, IL-8, and high-motility group box-1 (HMGB1) promote catabolism through systemic inflammation, resulting in tissue damage." (PMID 39125651, 2024). "Genes involved in mitogen‐activated protein kinase (MAPK) signaling, the TNF signaling pathway, pathways in cancer, protein processing in ER, and the apoptosis pathway were upregulated in CYB5R3-overexpressing cells." (PMID 38253797, 2024). "Increased vascular permeability, driven by cytokines such as IL-6 and tumor necrosis factor-α, facilitates the infiltration of cancer cells into lymphatic and blood vessels." (PMID 39156325, 2024). "Pro-inflammatory cytokines, including IL-6, IL-8, and TNF-α, serve as pivotal mediators in the intricate crosstalk between stromal and cancer cells." (PMID 38406163, 2024). "In particular, IL-2, TNF-α, and IL-6 play crucial roles in the immune response to inflammation as well as cancer." (PMID 39317690, 2024). "On the other hand, TNF-α which is a pro-inflammatory cytokine, serves as a mediator of the immune response, helping to eliminate cancer cells." (PMID 38915777, 2024). "In cancer stem cell types, the differentially regulated genes in different samples are mainly involved in the interleukin (IL)-17-signaling pathway, the tumor necrosis factor (TNF)-signaling pathway, and the like." (PMID 39382748, 2024). "Specifically, we examined the molecular mechanisms by which tumor necrosis factor (TNF) influences cancer metastasis." (PMID 39600368, 2024). "GO and KEGG analyses showed that the differentially expressed genes (DEGs) were mainly enriched in cancer-related programs or signalling pathways, such as the TNF signalling pathway, IL-17 signalling pathway and cytokine-cytokine receptor interaction." (PMID 38579171, 2024). "Despite its name, TNFα was initially anticipated to revolutionize cancer treatment upon its discovery." (PMID 38610706, 2024).